TLR3 (toll like receptor 3)
Diseases named in the same sentence as TLR3 in open-access papers (continued):
Sharing a sentence is not in itself a finding about the gene and the disease.
meningoencephalitis (4 papers, 2015 to 2024). Inflammation of the meninges and brain, generally secondary to an infectious cause. "Also, there was a pathway association between TLR3-TRIF SNPs and multiple symptoms of hemorrhagic fever, as well as 3 or more symptoms of meningoencephalitis, which suggests that this innate pathway is important in the pathogenesis of RVFV-associated severe disease." (PMID 25756647, 2015). "Moreover, TLR3 missense mutations and rare genetic variants of TLR3 that have not yet been functionally characterized were recently reported in patients with VZV encephalitis, influenza-associated encephalopathy, and tick-borne encephalitis virus (TBEV) meningoencephalitis." (PMID 38997413, 2024).
myocardial ischemia (4 papers, 2018 to 2024). A disorder of cardiac function caused by insufficient blood flow to the muscle tissue of the heart. "Previous studies testing TLR3‐KO mice in the model of myocardial ischemia/reperfusion (I/R) have reported conflict results." (PMID 28945004, 2018).
pancreatic adenocarcinoma (4 papers, 2019 to 2025). "To identify the role of cancer cell TLR3, we compared its expression in Panc1 and Cfpac cells (human pancreatic adenocarcinoma cell lines) with Hpne cells (human pancreatic ductal cell line) by immunofluorescence." (PMID 40675966, 2025). "Moreover, we investigated the associations of TLR3 expression and somatic copy number alterations (SCNA) with the immune cells infiltration levels in kidney renal clear cell carcinoma (KIRC), brain lower grade glioma (LGG) and pancreatic adenocarcinoma (PAAD)." (PMID 36419829, 2022).
paracoccidioidomycosis (4 papers, 2018 to 2025). A systemic fungal infection caused by Paracoccidioides brasiliensis that is most often seen in immunocompromised patients. "As conclusion, we suggest that TLR3 could be used as an escape mechanism of the fungus in an experimental paracoccidioidomycosis." (PMID 30687643, 2018). "Similarly, in paracoccidioidomycosis (PCM), TLR3 facilitates fungal immune evasion by inhibiting the activation and cytotoxic function of IFN-γ+CD8+ T and IL-17+CD8+ T cells." (PMID 41293166, 2025).
primary immunodeficiencies (4 papers, 2020 to 2022). "In neonatal severe forms or prolonged forms in infancy, primary immunodeficiency must be suspected and excluded, based on recent data demonstrating mutations of Toll-like receptor 3 and type 1 interferon in patients with severe SARS-CoV-2 pneumonia." (PMID 33917940, 2021).
reovirus infection (4 papers, 2015 to 2022). "This study warrants the necessity to delineate at the molecular level the mechanism adopted by TLR3 in reovirus infection and propagation with special emphasis on KRAS mutated CRC condition as a progress towards search of a better therapy of KRAS mutated CRC." (PMID 28422714, 2017). "We next performed real time PCR to quantify the expression of RNA-dependent RNA polymerase Lambda 3 in HCT116 and HCT116 TLR3 KO cells at 24 hours’ post reovirus infection." (PMID 28422714, 2017). "These three assays distinctly reveal that downstream activation of the respective interferons was completely compromised post reovirus infection in TLR3 down regulated HCT116 cells." (PMID 28422714, 2017).
sarcoidosis (4 papers, 2010 to 2024). Sarcoidosis is a multisystemic disorder of unknown cause characterized by the formation of immune granulomas in involved organs. "Specifically, LYST, a regulator of endosome/lysosome trafficking, can regulate TLR3 and TLR4 mediated pathways, genes involved in the innate immune system which have been implicated in sarcoidosis." (PMID 39080656, 2024). "An overexpression of TLR-3 mRNA was found in fibrotic disorders (CTD-IPs/IPF) in comparison with sarcoidosis (mean ± SD, 1.104 ± 1.087 versus 0.038 ± 0.03; P = 0.04)." (PMID 20937083, 2010). "In another study, the TLR3 polymorphism Leu412Phe (rs3775291), which was associated with accelerated disease progression and elevated mortality risk in IPF, was evaluated in patients with sarcoidosis." (PMID 36543347, 2022). "Moreover, patients with CTD-IP had an increased TLR-3 mRNA expression in comparison with sarcoidosis (mean ± SD, 2.03 ± 2 versus 0.038 ± 0.037; P = 0.002) and control subjects (mean ± SD, 2.03 ± 2 versus 0.0014 ± 0.0008; P = 0.05)." (PMID 20937083, 2010). "Enriched genes including MPO (myeloperoxidase), CXCL11, IL1A, CXCL10, FCGR3B, IL1B, TTN (titin), BATF2, VIP (vasoactive intestinal peptide), TLR3, CCR2, TLR7, and CR1 wereclosely related to sarcoidosis." (PMID 38137330, 2023). "TLR-3 mRNA expression was significantly higher in patients with fibrotic disorders (CTD-IPs and IPF) when compared to those with granulomatous disorders (sarcoidosis) (mean ± SD, 1.104 ± 1,087 versus 0.038 ± 0.037; P = 0.04)." (PMID 20937083, 2010). "Additionally, TLR-3 mRNA was increased in CTD-IPs in comparison with IPF (P = 0.001), sarcoidosis (P = 0.002) and controls (P = 0.05)." (PMID 20937083, 2010).
squamous cell carcinoma (4 papers, 2018 to 2024). A carcinoma arising from squamous epithelial cells. "Indeed, TLR3 expression was significantly associated with a good prognosis in adenocarcinoma (p < 0.001; HR = 0.58; n = 720) but not in squamous carcinoma (p = 0.91; HR = 1.01; n = 524)." (PMID 32093313, 2020). "Summarizing the Results section, significant differences were observed in the expression of various TLRs (TLR-2, TLR-3, TLR-4, TLR-7, TLR-8, and TLR-9) on selected T and B cell subpopulations between the patients with squamous cell carcinoma (SCC) and the healthy controls." (PMID 39124797, 2024).
Stevens-Johnson syndrome (4 papers, 2012 to 2023). Stevens-Johnson syndrome is a limited form of toxic epidermal necrolysis characterized by destruction and detachment of the skin epithelium and mucous membranes involving less than 10% of the body surface area. "This contrasted with putative TLR3-mediated OcS disease (Stevens-Johnson Syndrome, Mucous membrane pemphigoid) where an increase in cortisol∶cortisone ratio was observed (113.8∶1; p<0.05)." (PMID 24736562, 2014). "We have previously reported that TLR3 is a disease-associated gene in Stevens-Johnson syndrome (SJS), and there is a possibility that an abnormality in TLR3-related innate immune mechanisms is relevant to the pathogenesis of ocular surface inflammation in SJS5." (PMID 37193897, 2023).
thymoma (4 papers, 2015 to 2025). A neoplasm arising from the epithelial cells of the thymus. "Indeed, our patient harbors the heterozygous (p.Pro554Ser) missense variant in the TLR3 gene and is homozygous for the CCR5Δ32 deletion, but he was also affected by a thymoma causing production of anticytokine antibodies." (PMID 38976510, 2025). "This supports the activation of TLR3 signaling by EBER in MG-associated thymomas." (PMID 35894054, 2022). "An increase in the expression and activation of TLR3 was also observed in patients with MG and thymoma compared to controls, correlating with EBER1 levels." (PMID 35894054, 2022). "Indeed, our data not only confirmed TLR3 up-regulation in MG thymomas versus normal thymuses, but also demonstrated that the expression of this receptor was higher in thymomas from MG patients compared with non-MG." (PMID 29221139, 2017). "We confirmed increased transcriptional levels of TLR3 in MG thymomas compared with normal thymuses and, interestingly, we found that TLR3 was significantly overexpressed in MG-associated thymomas compared with thymomas from patients without MG." (PMID 29221139, 2017). "Interestingly, transcriptional levels of TLR3 positively correlated with EBER1 levels in EBV-infected MG thymomas, thus suggesting TLR3 signaling activation by EBERs in MG-associated thymomas." (PMID 29221139, 2017). "Increased TLR3 transcript levels in MG thymomas: possible activation by EBERs?" (PMID 29221139, 2017). "Recently, Cufi and collaborators demonstrated TLR3 overexpression in MG thymomas compared to normal thymuses, suggesting that TLR3-mediated pathways may be activated via pathogen-related dsRNAs in the neoplastic tissue of MG thymomas." (PMID 29221139, 2017). "In MG thymomas it has been recently reported a sustained IFN-mediated antiviral response and TLR3 overexpression; our data on EBV detection in MG thymomas raised the question whether the virus itself may play a significant role in the inflammatory processes." (PMID 29221139, 2017). "Here, we compared TLR3 expression between MG and non-MG thymomas, to verify whether TLR3 overexpression in MG thymomas was strictly linked to thymoma or instead was specific for MG." (PMID 29221139, 2017). "Toll-like receptor (TLR) 3 transcriptional levels were higher in MG than non-MG thymomas and positively correlated with EBER1 levels, suggesting a role for EBERs in TLR3 activation." (PMID 29221139, 2017).
thyroid cancer (4 papers, 2021 to 2024). "Also, upregulation of TLR3 has been associated with improved overall survival in thyroid cancer patients." (PMID 37803074, 2023). "Specifically, our data suggest activation of the TRIF-dependent pathway by TLR3 in thyroid carcinoma, which may be an essential receptor for radiation damage." (PMID 34306609, 2021). "In this study, we analyzed the expressions of TLR2, TLR3, TLR4, TLR5, TLR7, TLR9, MyD88, and TRIF by immunohistochemistry (IHC) to determine whether there is an association between thyroid carcinoma and innate immune responses." (PMID 34306609, 2021). "Cytoplasmic HMGB3 activates nucleic acid-mediated TLR3/NF-κB signaling, and extracellular HMGB3 interacts with the transmembrane receptor triggering receptor expressed on myeloid cells (TREM1 and CD354) in thyroid cancer." (PMID 39062899, 2024).
vitiligo (4 papers, 2015 to 2025). Generalized well circumscribed patches of leukoderma that are generally distributed over symmetric body locations and is due to autoimmune destruction of melanocytes. "SNP rs6552950 from TLR3 intron produced the only allelic association with vitiligo among males." (PMID 26442097, 2015). "From the point of innate immune responses, TLR3-mediated viral stimuli might be involved in the development of vitiligo." (PMID 33371432, 2020). "Specifically, TLR3 that is expressed in melanocytes may sense viral infection and induce apoptosis along with local immune response, that contributes to vitiligo development." (PMID 26442097, 2015).
acute liver failure (3 papers, 2013 to 2021). Rapid deterioration of liver function causing encephalopathy and coagulopathy. "Thus, the use of antibody directed against TLR3 might represent an attractive therapeutic approach for treatment of drug-induced acute liver failure." (PMID 23762449, 2013). "This study revealed impaired monocyte-macrophage functionality and reduced expression of TLR3, TLR7, and downstream signaling molecules in pregnant patients with acute liver failure (ALF), implicating the role of these PRRs in curtailing viral infection." (PMID 34502167, 2021). "However, patients with lower expression of TLR3 and IFN-γ progress to acute liver failure." (PMID 27656178, 2016).
allergic conjunctivitis (3 papers, 2012 to 2022). "Using a murine model of experimental allergic conjunctivitis as a model for ocular surface inflammation, we examined TLR3 gene function in TLR3 knock-out (KO)- and TLR3 transgenic (TLR3Tg) mice." (PMID 34869401, 2021).
aortic valve stenosis (3 papers, 2023 to 2025). Aortic valve stenosis (AVS) is a condition characterized by narrowing of the heart's aortic valve opening. "For example, TLR3 knockout mice or pharmacological inhibition of TLR3 in vivo prevented the development of aortic valve stenosis." (PMID 39828779, 2025).
breast tumor (3 papers, 2012 to 2013). "In corroboration with the work reported herein, Conforti and colleagues recently showed that in vivo injection of poly(A:U), a TLR3 agonist, in combination with an immunochemotherapeutic regimen, was able to inhibit TLR3 positive breast tumor growth." (PMID 23056170, 2012). "However, there is direct and indirect pre-clinical as well as clinical evidence that TLR3 impacts breast tumor viability and/or behavior using TLR3-specific agonists, namely polyadenylic-polyuridylic acid [poly(A:U)] and polyinosinic-polycytidylic [poly(I:C)]." (PMID 24194738, 2013).
cardiomyopathy (3 papers, 2018 to 2024). A disease of the heart muscle or myocardium proper. "In the absence of either TLR3 or TLR9, the intensity of echocardiogram (Echo)-Doppler dysfunction during development of cardiomyopathy was substantially reduced in the K.O. mice." (PMID 30364002, 2018).
cerebral infarction (3 papers, 2015 to 2022). An ischemic condition of the brain, producing a persistent focal neurological deficit in the area of distribution of the cerebral arteries. "Poly (I:C) administration did not reduce cerebral infarction in TLR3−/− mice, indicating that poly (I:C)-induced protection was lost in TLR3−/− mice." (PMID 25351293, 2015).
cholesteatoma (3 papers, 2014 to 2021). A pathologic process characterized by the proliferation of keratinizing squamous epithelium resulting in the accumulation of keratin and cells in the middle ear and/or mastoid. "We have reported that TLR2, TLR3, and TLR4 are expressed in epithelial cells, including human acquired cholesteatoma and cancer cells." (PMID 25385222, 2015). "From immunohistochemistry studies of biopsies from the normal ear canal and acquired cholesteatoma (an abnormal growth of keratinized squamous epithelium), it appears that expression of TLR2, TLR3 and TLR4 is detected and regulated as a function of cholesteatoma." (PMID 25161655, 2014).
chronic mucocutaneous candidiasis (3 papers, 2016 to 2025). "Moreover, defects in intrinsic and innate immunity, including TLR-3 deficiency and chronic mucocutaneous candidiasis, were linked to pathogenic variants in TLR3 and STAT1, respectively, through autosomal inheritance." (PMID 40806973, 2025). "TLR3, as one of a number of key pattern recognition receptors, plays an important role in recognizing multiple pathogens, such as viruses and fungi, while the patients with Aire mutation usually suffered from chronic mucocutaneous candidiasis." (PMID 27916941, 2016). "Deficiencies in intrinsic and innate immunity accounted for another 1.11%, comprising individuals with Toll-like receptor 3 (TLR-3) deficiency and chronic mucocutaneous candidiasis (CMC)." (PMID 40806973, 2025). "The non-synonymous SNP rs3775291 (Leu412Phe) in TLR3 has been identified more frequently in patients suffering from chronic mucocutaneous candidiasis (CMC)." (PMID 41295183, 2025).
Cognitive impairment (3 papers, 2015 to 2023). Abnormal cognition is characterized by deficits in thinking, reasoning, or remembering. "Based on our observations, we propose that TLR3 plays a vital part in cognitive impairment after CCI." (PMID 37544956, 2023). "In this study, TLR3 deletion was discovered to ameliorate repeat sevoflurane exposure-induced cognitive impairment in neonatal mice, inhibit RIP3 phosphorylation and reduce the programmed necrosis of hippocampal neurons." (PMID 35666713, 2022). "Supporting to this, earlier study demonstrated that TLR-3 activation possibly negatively regulate ERK-CREB signaling, thus, activation of TLR-3 contribute to cognitive impairment and other behavioral disorders." (PMID 26388777, 2015). "To determine the reason why peripheral nerve neuropathic pain can cause central nervous system inflammation and other responses leading to cognitive impairment, we hypothesized that after the sciatic nerve was damaged, exRNAs/dsRNAs were released; thus, TLR3 was activated in the hippocampus." (PMID 37544956, 2023).
cryptococcosis (3 papers, 2015 to 2023). An acute or chronic, localized or disseminated infection by Cryptococcus neoformans. "Protection from cryptococcosis by pICLC-induced Type I IFN was mediated by MDA5 rather than TLR3." (PMID 26252005, 2015). "However, our data do not rule out the possibility that specifically triggering TLR3 by other means might also be protective against cryptococcal infection." (PMID 26252005, 2015).
Cryptosporidium infection (3 papers, 2016 to 2023). "Cryptosporidiosis is most dangerous in children below the age of two years and it is thus noteworthy that TLR3 is poorly expressed in neonates, and that low levels of TLR3 in the intestinal epithelium have been linked to the heightened susceptibility of neonatal mice to rotavirus." (PMID 35584177, 2022). "We also determined that TLR3 was the pattern recognition receptor responsible for IFNλ production during Cryptosporidium infection." (PMID 35584177, 2022). "Signaling TLR3 in combination with TLR5, TLR4 and TLR9 independently influence Cryptosporidium infection outcomes." (PMID 27467505, 2016). "The absence of TLR3 signaling can impair the production of IL-12 by DCs which is important for the control of Cryptosporidium infection." (PMID 35584177, 2022). "We found the production of IL-18, an enterocyte derived cytokine induced by Cryptosporidium infection, to be intact in the absence of TLR3 (Standard t-test *** p <0.001)." (PMID 35584177, 2022).
cutaneous leishmaniasis (3 papers, 2018 to 2021). Leishmaniasis affecting the skin. "Finally, as NLR and RLR pathways are the major non-TLR3 routes of dsRNA-induced inflammation, this work confirmed TLR3 as the major pathway of inflammatory pathology in LRV1-mediated cutaneous leishmaniasis." (PMID 29487860, 2018).
dermatitis (3 papers, 2021 to 2024). An inflammatory process affecting the skin. "Additional processes contribute to the dermatitis caused by the cpd mutation of Sharpin, including TLR3 signaling, NLRP3 inflammasome and IL-1β signaling, and IL-4 signaling." (PMID 38156288, 2024). "TLR3 is expressed in the epidermis of the skin and it positively regulates skin inflammation, and it is possible that innate immunity such as TLR3 might contribute to mucocutaneous inflammation seen in SJS/TEN with SOC." (PMID 35899189, 2022).
epilepsy (3 papers, 2023 to 2024). A brain disorder characterized by episodes of abnormally increased neuronal discharge resulting in transient episodes of sensory or motor neurological dysfunction, or psychic dysfunction. "Similarly, mutations in the gene encoding for toll-like receptor 3 (TLR3) can cause another rare form of epilepsy, which is characterized by severe brain inflammation and seizures triggered by herpes simplex virus infection." (PMID 38612542, 2024). "Future studies addressing the mechanisms underlying the role of TLR3 inhibition in epileptogenesis prevention will broaden our understanding of the processes involved in neuroinflammation-mediated epilepsy and pave the path toward novel and improved anti-epilepsy drugs." (PMID 37694107, 2023). "Based on these results, it can be considered that epilepsy may be associated with TLR3." (PMID 39046369, 2024). "Our results provide substantial evidence to the importance of TLR3 inhibition in the prevention of epilepsy and specifically highlighting FC99 as a promising novel anti-epileptic drug." (PMID 37694107, 2023). "The clinical benefits of these and other TLR3 blockers should be further studied to develop novel therapeutics for epilepsy." (PMID 37694107, 2023). "Toll-like receptor 3 (TLR3), plays an important role in the development of epilepsy after brain insults." (PMID 37694107, 2023). "TLR3 was mostly expressed in both the T. gondii positive and epilepsy groups." (PMID 39046369, 2024).